RNF224 (ring finger protein 224)
Tractability: No criterion of Open Targets' tractability assessment is met for any kind of drug.
Gene: Protein-coding gene on chromosome 9 (137,226,908 to 137,229,640, forward strand). Ensembl gene ENSG00000233198.
Subcellular location (Human Protein Atlas): Golgi apparatus; Nucleoplasm
Genetic constraint (gnomAD): Loss-of-function variants: 1 observed, 1.93 expected, observed/expected ratio (o/e) 0.52, 90% interval 0.17 to 1.76. That is too few expected variants to judge how well the gene tolerates losing a copy. Missense variants: 244 observed, 203.92 expected, observed/expected ratio (o/e) 1.2, 90% interval 1.08 to 1.33. Synonymous variants: 112 observed, 89.3 expected, observed/expected ratio (o/e) 1.25, 90% interval 1.08 to 1.47.
Homologues: Orthologues: chimpanzee RNF224 (98% identical), pig RNF224 (74% identical), dog RNF224 (71% identical), rat Rnf224 (69% identical), mouse Rnf224 (67% identical), zebrafish rnf224 (43% identical), tropical clawed frog RNF224 (38% identical), Drosophila melanogaster roq (19% identical). Paralogues in human: RNF227 (29% identical), RNF228 (21% identical), RNF182 (21% identical), RC3H1 (20% identical), RC3H2 (20% identical).